C9orf50 (chromosome 9 open reading frame 50)
Synonyms: FLJ35803
Tractability: PROTAC: ubiquitination databases record sites on it.
Gene: Protein-coding gene on chromosome 9 (129,612,225 to 129,621,101, reverse strand). Ensembl gene ENSG00000179058.
Subcellular location: Cytoplasm
Gene Ontology:
Cellular component: cytoplasm
Genetic constraint (gnomAD): Loss-of-function variants: 33 observed, 35.46 expected, observed/expected ratio (o/e) 0.93, 90% interval 0.7 to 1.25. The upper end of that interval is the gene's LOEUF score, 1.25, which puts it in group 5 of 6, group 1 being the genes least tolerant of losing a copy. Missense variants: 547 observed, 481.29 expected, observed/expected ratio (o/e) 1.14, 90% interval 1.06 to 1.22. Synonymous variants: 257 observed, 214.25 expected, observed/expected ratio (o/e) 1.2, 90% interval 1.08 to 1.33.
Homologues: Orthologues: chimpanzee C9H9orf50 (97% identical), macaque C15H9orf50 (88% identical), dog C9orf50 (54% identical), rat C3h9orf50 (43% identical), mouse 1700001O22Rik (40% identical).
Diseases named in the same sentence as C9orf50 in open-access papers:
C9orf50 is named in the same sentence as 15 diseases in open-access papers, as found by Europe PMC text mining. Sharing a sentence is not in itself a finding about the gene and the disease. The quoted sentences say what the papers report.
colorectal cancer (7 papers, 2013 to 2025). A primary or metastatic malignant neoplasm that affects the colon or rectum. "Sensitivities of methylated KCNQ5 and methylated C9orf50 in stool DNA for detecting colorectal cancer (CRC) in different genders, age groups, stages, tumor locations, tumor sizes, and differentiation statuses." (PMID 33585248, 2020). "Future work should explore the function and immunomodulatory effects of C9ORF50 in KRAS‐mutant colorectal cancer models to determine whether its role remains conserved across different genetic backgrounds." (PMID 41472851, 2025). "Moreover, a recent genome-wide screen using DNA methylation data from more than 700 colorectal cancer samples identified hypermethylation of the thrombin receptor THBD and of C9orf50 as novel blood-based biomarkers for colorectal cancer detection." (PMID 25473433, 2014). "A genome-wide scale study with plasma and serum samples from 107 colorectal cancer patients and 98 individuals without colorectal cancer revealed that analysis of methylated THBD and C9orf50 outperformed carcinoembryonic antigen (CEA) measurement for early colorectal cancer detection." (PMID 23681012, 2013). "To elucidate the relationship of C9ORF50 and immune infiltration in the TME, we performed histology and immunofluorescence analysis on human colorectal cancer samples." (PMID 41472851, 2025). "Three DNA methylation markers, C9orf50, KCNQ5, and CLIP4, can discriminate between the plasma from colorectal cancer patients and that of healthy individuals." (PMID 33575272, 2020). "Three DNA methylation markers, C9orf50, KCNQ5, and CLIP4, were identified, each capable of discriminating plasma from colorectal cancer patients and healthy individuals (areas under the curve 0.86, 0.91, and 0.88)." (PMID 31727158, 2019). "Furthermore, qPCR analysis of 12 matched pairs of colorectal cancer tissues and adjacent noncancerous tissues revealed a significant upregulation of C9ORF50 in malignant tissues." (PMID 41472851, 2025). "Aberrant DNA methylation has emerged as a class of promising biomarkers for early colorectal cancer (CRC) detection, but the performance of methylated C9orf50 and methylated KCNQ5 in stool DNA has never been evaluated." (PMID 33585248, 2020).
adenoma (3 papers, 2019 to 2021). A neoplasm arising from the epithelium. "They target CpG sites located in the 5′-regions of the genes C9orf50, KCNQ5, and CLIP4 that were found to be concurrently hypermethylated in CRC and adenoma tissues, but unmethylated in blood cells and in most other cancer types." (PMID 31727158, 2019).
melanoma (2 papers, 2012 to 2025). A malignant, usually aggressive tumor composed of atypical, neoplastic melanocytes. "To further investigate whether C9orf50 knockout affects the growth of other cancer types, we knocked out C9orf50 in Hepa1‐6 (Hepatoma), Pan02 (pancreatic cancer), E0771 (triple‐negative breast cancer), and B16F10 (melanoma), and transplanted these cells into C57BL/6 mice." (PMID 41472851, 2025).
colon adenocarcinoma (1 paper, 2025). "Elevated C9ORF50 expression was significantly associated with advanced clinical staging in colon adenocarcinoma." (PMID 41472851, 2025).
colorectal tumor (1 paper, 2025). "Similarly, in orthotopic colorectal tumor models, C9orf50 knockout significantly reduced tumor growth compared to the NTC controls." (PMID 41472851, 2025).
gastric cancer (1 paper, 2025). A primary or metastatic malignant neoplasm involving the stomach. "While C9ORF50 has not been functionally characterized, prior studies have linked its aberrant DNA methylation to early diagnostic biomarkers for colorectal and gastric cancers, suggesting its involvement in gastrointestinal cancers." (PMID 41472851, 2025).
cancer (6 papers, 2012 to 2025). A tumor composed of atypical neoplastic, often pleomorphic cells that invade other tissues. "In summary, our study identifies C9ORF50 as a previously uncharacterized spliceosome‐associated protein and a candidate target for cancer immunotherapy." (PMID 41472851, 2025). "Collectively, these findings suggest that C9orf50 knockout enhances tumor rejection in various cancer types, particularly those of gastrointestinal origin." (PMID 41472851, 2025). "To evaluate the potential of C9orf50 as a cancer therapeutic target, we investigated the antitumor effects of C9orf50 inhibition via direct intratumoral administration of C9orf50 siRNA (siC9ORF50) in MC38 tumor‐bearing mice." (PMID 41472851, 2025). "Further analysis of clinical samples revealed a significant inverse correlation between C9ORF50 expression and adaptive immune cell infiltration and patient prognosis, reinforcing its potential as a cancer therapeutic target." (PMID 41472851, 2025). "Together, these findings indicate that C9orf50 depletion activates the cytoplasmic dsRNA‐sensing pathway, leading to potent innate immune responses in cancer cells, potentially contributing to antitumor immunity." (PMID 41472851, 2025). "Collectively, these results suggested that C9orf50 represents a promising target for cancer therapy." (PMID 41472851, 2025). "To explore the clinical relevance of our findings, we analyzed C9ORF50 expression in human cancer cohorts." (PMID 41472851, 2025). "Examination of clinical samples revealed that C9ORF50 expression is inversely correlated with cancer patient prognosis." (PMID 41472851, 2025). "Collectively, these findings establish a compelling association between C9ORF50 overexpression and the establishment of an immunosuppressive TME, ultimately contributing to poor patient survival outcomes across multiple cancer types." (PMID 41472851, 2025). "We identify C9ORF50 as a novel splicing regulator whose inhibition profoundly sensitizes cancer to immune surveillance." (PMID 41472851, 2025). "The genetic knockout of C9orf50 induces an intrinsic innate immune response in cancer cells by disrupting splicing, thereby transforming immunologically cold tumors into inflamed phenotypes characterized by increased T cell infiltration and enhanced antitumor activity." (PMID 41472851, 2025). "Thus, C9orf50, C9orf64, C5orf66, C16orf74 and C10orf55 genes are most mentioned in the cancer context (each gene was mentioned at least in six publications), while 42 out of 92 genes are mentioned in one publication only." (PMID 37373333, 2023). "Although a CLIP4 signal in plasma suggests the presence of tumor DNA when corroborated by KCNQ5 or C9orf50, the suboptimal performance of CLIP4 in gastric and GEJ cancers should be noted." (PMID 39369091, 2025). "We showed that THBD and C9orf50 harbor low levels of DNA methylation in 15 types of cancer other than CRC, including most high-incidence cancers." (PMID 23209692, 2012). "In this study, through an in vivo genome‐wide CRISPR screen in syngeneic colorectal models, we have identified C9orf50, a gene previously lacking characterization, as a novel target for cancer immunotherapy." (PMID 41472851, 2025). "Conversely, among the top five prognostic mRNAs estimated by Multi-PEN, C9orf50 has not been extensively studied regarding its relationship with LGG or other cancers." (PMID 36290366, 2022).
tumor (5 papers, 2012 to 2025). "Collectively, these findings suggest C9orf50 deficiency primarily drives tumor regression via T cell‐dependent immunity, with a subsidiary contribution from extrinsic apoptosis in tumor cells." (PMID 41472851, 2025). "Notably, IF staining analyses for dsRNA on mouse tumor tissues robustly demonstrated that C9orf50 deficiency induces profound dsRNA accumulation, further corroborating the cell‐based findings in vivo." (PMID 41472851, 2025). "A tumor-agnostic strategy was applied to detect ctDNA using a multiplex ddPCR assay targeting the DNA methylation markers C9orf50, KCNQ5, and CLIP4." (PMID 39369091, 2025). "Together, these findings reveal that C9ORF50 inhibition effectively converts immune‐suppressive tumors into T cell‐inflamed lesions, thereby enhancing immunogenicity and suppressing tumor growth." (PMID 41472851, 2025). "Our work identifies C9ORF50 as a candidate therapeutic target that modulates RNA splicing and tumor immunity, suggesting splicing regulation as a potential strategy to enhance immunotherapy responses." (PMID 41472851, 2025). "Consistent with our observations in the MC38 model, C9orf50 knockout in these cells significantly inhibited tumor growth and resulted in better survival compared to NTC controls." (PMID 41472851, 2025). "Given the limited understanding of the uncharacterized gene C9orf50 identified in our screen, we sought to investigate its role in tumor growth and immune surveillance." (PMID 41472851, 2025). "As a result, C9ORF50 inhibition amplifies tumor cell immunogenicity, enhancing T cell infiltration in poorly infiltrated tumors." (PMID 41472851, 2025). "Among them, we identified C9ORF50, a previously uncharacterized gene whose knockout resulted in significant tumor regression and improved survival." (PMID 41472851, 2025). "In our previous studies, we have demonstrated a high sensitivity of ctDNA detection using the TriMeth test, a tumor-agnostic multiplex droplet digital PCR assay targeting the gastrointestinal cancer-specific DNA methylation markers, C9orf50, KCNQ5, and CLIP4." (PMID 39369091, 2025). "Therapeutic targeting of C9ORF50 using RNA interference enhances T cell infiltration and suppresses tumor growth." (PMID 41472851, 2025). "The relatively tumor‐enriched expression pattern and non‐essential role in normal mouse physiology suggest C9ORF50 as a promising target for further therapeutic development, though a comprehensive safety evaluation will be necessary." (PMID 41472851, 2025). "Tumor growth curves revealed that C9orf50 knockout MC38 cells formed significantly smaller tumors in immunocompetent C57BL/6 mice compared to NTC controls." (PMID 41472851, 2025). "Notably, therapeutic targeting of C9ORF50 via intratumoral administration of siRNA led to a dramatic reduction in tumor burden, underscoring its potential as a novel immunotherapy target." (PMID 41472851, 2025). "Histopathological analysis showed reduced tumor cell density in tumors treated with C9orf50 siRNA." (PMID 41472851, 2025). "C9orf50 knockout only resulted in a modest reduction in tumor growth compared to controls." (PMID 41472851, 2025). "Moreover, in subcutaneous tumor tissues derived from C9orf50‐knockout cells, phosphorylation of IRF3 was also significantly enhanced." (PMID 41472851, 2025). "Third, while tumor‐infiltrating lymphocytes increase after C9ORF50 inhibition, we have not assessed whether C9ORF50 loss impairs normal T cell activation or effector functions." (PMID 41472851, 2025). "Collectively, the relatively tumor‐specific expression pattern, combined with the non‐essential nature of C9ORF50 in normal physiology, strongly suggests that targeted inhibition of this protein may represent a promising therapeutic strategy with inherently constrained potential deleterious effects." (PMID 41472851, 2025).
tumor (continued). "Further analysis demonstrated that C9orf50 knockout does not significantly affect tumor cell proliferation but induces apoptosis both in vivo and in vitro." (PMID 41472851, 2025). "(ii) Tumor cells may rely on C9ORF50 for spliceosome assembly in a way that normal tissues do not, suggesting a unique dependency on distinct splicing mechanisms in malignancies." (PMID 41472851, 2025).
C9orf50 also shares sentences with these, for which no sentence is quoted: acute myeloid leukemia (1 paper); bladder cancers (1); breast carcinoma (1); glioblastoma multiforme (1); head and neck squamous cell carcinoma (1); Hepatoma (1); pancreatic cancer (1).